TNKS (tankyrase)
Diseases named in the same sentence as TNKS in open-access papers (continued):
Sharing a sentence is not in itself a finding about the gene and the disease.
infection (5 papers, 2013 to 2023). The state of being infected such as from the introduction of a foreign agent such as serum, vaccine, antigenic substance or organism. "Stress granules, composed of aggregates of proteins and RNA within the cytosol, can form during infection – these contain heavily PARylated proteins, Tankyrase 1 and PARPs 12 to 15, as well as PARG." (PMID 34485381, 2021). "Using a semi-quantitative assay, we observed a decrease in the auto-PARsylation activity of TNKS upon infection, which should be expected to reduce its degradation." (PMID 26729153, 2015). "Infection leads to accumulation and stabilization of TNKS in infected cells resulting from its enzymatic inhibition and reduced PARsylation activity." (PMID 26729153, 2015). "HCMV slows down the PARsylation activity of TNKS, which is reflected in its accumulation during infection." (PMID 26729153, 2015). "Although the direct mechanism by which HCMV inactivates TNKS activity remains to be elucidated, it is possible that viral or even cellular proteins induced by infection interact with TNKS and slow down its enzymatic activity." (PMID 26729153, 2015). "In our study, the tankyrase inhibitors Endo-IWR-1 and JW67 inhibited RVFV MP12-GFP infection by greater than 50% in RVFV disease-relevant primary human hepatocytes, and JW67 significantly reduced infection of cells with wild-type RVFV, LCV, and CEV." (PMID 27226375, 2016). "Starting at 24 h post infection, HCMV stabilized the expression of TNKS and reduced its PARsylation activity, resulting in accumulation of Axin1 and reduction in its PARsylation as well." (PMID 26729153, 2015). "However, qRT-PCR at 24 hpi revealed that mRNA levels of TNKS 1 and 2 were not significantly changed during infection, indicating the upregulation of TNKS was a post-transcriptional effect." (PMID 26729153, 2015). "The effect of XAV939 on β-catenin expression may be both time- and cell-dependent, since in HFFs, despite the accumulation of TNKS and Axin1, the expression of β-catenin was determined largely by infection and not by XAV939." (PMID 26729153, 2015). "Infection resulted in reduced levels of β-catenin, irrespective of the amount of Axin or TNKS." (PMID 26729153, 2015). "Stable infection of ED1L (data not shown) or ED1 with a lentiviral vector containing a luciferase gene cassette under control of a 7× TCF binding site promoter allowed for monitoring of the transcriptional activity of the Wnt pathway during TNKS inhibition." (PMID 23621985, 2013). "A significant and reproducible difference in the level of ubiquitinated TNKS between non-infected and HCMV-infected human foreskin fibroblasts (HFFs) was observed, suggesting that the ubiquitination status of TNKS was increased, rather than decreased upon infection." (PMID 26729153, 2015).
adenocarcinoma (2 papers, 2013 to 2024). A common cancer characterized by the presence of malignant glandular cells. "Xiaoyan decoction and E7449 suppressed TNKS expression and inhibited adenocarcinoma cell proliferation, migration, invasion and apoptosis in vitro." (PMID 38898581, 2024). "Despite being closely-related cell lines derived from adenocarcinomas of mice differing only in the proteasomal susceptibility of their human cyclin E transgene, the molecular and growth phenotypic responses of the ED1 and ED2 cell lines to TNKS inhibition differed." (PMID 23621985, 2013).
TNKS also shares sentences with these, for which no sentence is quoted: glioblastoma (3 papers); neuroblastoma (3); Pancreatic Cancer (3); bladder cancer (2); depression (2); developmental delay (2); Insulin resistance (2); metabolic disease (2); non-Hodgkin lymphoma (2); small cell lung carcinoma (2); type II diabetes (2); amyotrophic lateral sclerosis (1); Arthritis (1); astrocytoma (1); B-cell neoplasm (1); bipolar disorder (1); bone cancer (1); Burkitt lymphoma (1); cardiac hypertrophy (1); cardiovascular disease (1); Cirrhosis (1); congenital heart disease (1); COVID-19 (1); degenerative diseases (1); diaphragmatic hernia (1); endometrial cancer (1); Hyperglycemia (1); Insulinoma (1); Intellectual disability (1); intestinal tumors (1).
A further 20 diseases each share a sentence with TNKS in 1 paper.